MMP9 (matrix metallopeptidase 9)
Diseases named in the same sentence as MMP9 in open-access papers (continued):
Sharing a sentence is not in itself a finding about the gene and the disease.
multiple sclerosis (70 papers, 2009 to 2026). A progressive autoimmune disorder affecting the central nervous system resulting in demyelination. "For example, in cases of optic neuritis associated with multiple sclerosis, elevated levels of both total MMP-9 and NfL were observed in the CSF of patients compared to healthy controls." (PMID 41009467, 2025). "Elevated MMP-9 levels have been reported in several autoimmune diseases, such as systemic lupus erythematosus and multiple sclerosis, and mainly linked to the increased accumulation of blood cells." (PMID 36358365, 2022). "ZnT3 gene deletion also remarkably inhibited formation of multiple sclerosis-associated aberrant synaptic zinc patches, MMP-9 activation, and BBB disruption." (PMID 28956834, 2017). "In multiple sclerosis MMP-9 causes increased permeability of the blood brain barrier, leading to greater inflammatory infiltration and it subsequently enhances demyelinisation and neuronal damage." (PMID 23139770, 2012). "It was demonstrated that the allele T of the MMP-9-1562C/T polymorphism was associated with an increased risk of susceptibility to multiple sclerosis, therefore, it may predispose them to MS development." (PMID 37206663, 2023). "In the case of the relationship between the MMP-9-1562C/T polymorphism and the risk of multiple sclerosis, it can be said that the T allele of the MMP-9-1562C/T polymorphism is associated with a higher incidence of multiple sclerosis, as well as with a worse course of the disease." (PMID 37206663, 2023). "Moreover, polymorphisms of the MMP-9 gene have been associated with higher risk of developing multiple sclerosis." (PMID 36358365, 2022). "Because of the functional implications of the −1562 C/T polymorphism of the MMP9 gene, the comorbidity of cardiovascular disorders, cancer, and such neuropsychiatric illnesses as schizophrenia, bipolar mood disorder, and multiple sclerosis can be hypothesized." (PMID 20037727, 2009). "For example, T cells can cross the BBB and attack myelin via MMP-9, together with B-cell-derived IL-6, leading to astrocyte reactivity and thus resulting in demyelination in multiple sclerosis." (PMID 41425563, 2025). "MMP-9 transcripts were undetectable in control CSF, while all multiple sclerosis samples were positive with similar levels during relapses versus clinically stable phases of the disease." (PMID 37175729, 2023). "Animal studies showed that blocking MMP-9 reduced neuroinflammation in multiple sclerosis animal model." (PMID 36059515, 2022). "The only pathology in which 65 kDa MMP-9 has been suggested as a biomarker is, to our knowledge, multiple sclerosis (MS)." (PMID 35723387, 2021). "Gelatinase B/matrix metalloproteinase-9 (MMP-9) triggers multiple sclerosis (MS) and the animal model of experimental autoimmune encephalomyelitis (EAE) by the breakdown of the blood-brain barrier." (PMID 30273366, 2018). "This characteristic seems to be shared by other chronic inflammatory disorders since increased expression of MMP-9 mRNA in blood mononuclear cells has been demonstrated in multiple sclerosis and systemic lupus erythematosus." (PMID 25153995, 2014). "The matrix metalloproteinases (MMPs) gelatinase A (MMP-2) and gelatinase B (MMP-9) are mediators of brain injury in multiple sclerosis (MS) and valuable biomarkers of disease activity." (PMID 24616914, 2014). "In any case, reactive astrocytes and activated microglia both produce MMP-2 and MMP-9 in a number of CNS disorders, including AD and multiple sclerosis." (PMID 24188129, 2013). "Inhibition of MMP-9 is discussed as a therapeutic strategy for multiple sclerosis, since inhibition of MMP-9 by Interferon-β led to reduced transmigration and decreased permeability of the blood brain barrier in patients." (PMID 23139770, 2012).
multiple sclerosis (continued). "MMP9 has also been shown to be elevated in multiple sclerosis (MS) and levels have been correlated to severity of MRI findings correlating with an increased number of gadolinium-enhancing MRI lesions or with the risk of developing new lesions." (PMID 23185624, 2012). "Based on the results of these studies, I hypothesize that the MMP9 gene, which has a functional −1562 C/T polymorphism, may mediate the epidemiological comorbidity of neuropsychiatric illnesses (schizophrenia, bipolar mood disorder, multiple sclerosis) with cardiovascular diseases and cancer." (PMID 20037727, 2009). "In mice fed with a high ω-3 PUFA diet, it was demonstrated that MMP-9 immunoreactivity decreased in aortic tissue and, in patients with sclerosis multiple, omega-3 fatty acid supplementation for 3 months decreased MMP-9 levels from peripheral blood mononuclear cells." (PMID 37378834, 2024). "Furthermore, higher MMP-9 levels have repeatedly been reported in neurological conditions, including multiple sclerosis, encephalomyelitis, and dementia." (PMID 38431757, 2024). "The polymorphism of MMP-9-1562C/T affects the activity of the MMP-9 promoter, may also affect the fluctuations of MMP-9 in multiple sclerosis." (PMID 37206663, 2023). "MMP-9 levels can increase in pathological conditions, such as multiple sclerosis and meningitis, and may become detectable also in the cerebrospinal fluid of patients with inflammatory diseases of the central and peripheral nervous system." (PMID 36358365, 2022). "However, studies on multiple sclerosis (MS) patients have correctly shown that active MMP-9 can be represented by two different isoenzymes, the 82 and 65 kDa isoforms and that this latter is the predominant active isoform associated with MRI activity in MS." (PMID 35723387, 2021). "For instance, it is established that proteolysis of interferon-β (IFN-β) by MMP-9 is hindered by glycosylation and that, maybe thereby, less neutralizing antibodies are formed in multiple sclerosis (MS) patients treated with glycosylated IFN-β." (PMID 34276694, 2021). "High levels of MMP-9 have been observed in the CSF of human patients and animals affected by neurological diseases that involve intense neuroinflammation, such as visceral leishmaniasis, traumatic cerebral injury, meningitis and multiple sclerosis." (PMID 25879519, 2015). "Repression of MMP-9 is an integral part of IFNβ’s efficacy as a therapeutic for multiple sclerosis." (PMID 22879913, 2012). "Enhanced expression of MMP-9 is involved in diverse pathological processes such as metastasis, tumor induced angiogenesis, and inflammatory conditions including rheumatoid arthritis, multiple sclerosis, lupus, and asthma." (PMID 22879913, 2012). "However, it is conceivable that the MMP9 gene is a mediating factor among cardiovascular disorders, cancer, schizophrenia, bipolar mood disorder, and multiple sclerosis." (PMID 20037727, 2009). "Furthermore, I hypothesize that the MMP9 gene, as shown by functional −1562 C/T polymorphism studies, may be mediating the relationship of neuropsychiatric illnesses (schizophrenia, bipolar mood disorder, multiple sclerosis) that are comorbid with cardiovascular disease and cancer." (PMID 20037727, 2009). "The MMP-9 activity in the brain is strictly regulated, and any disruptions in this regulation contribute to a development of many disorders of the nervous system including multiple sclerosis, brain strokes, neurodegenerative disorders, brain tumors, schizophrenia, or Guillain-Barré syndrome." (PMID 37206663, 2023). "Also, the expression of miR-320a that targets MMP9 mRNA, was significantly decreased in B cells in patients with multiple sclerosis and may contribute towards an increased blood-brain barrier permeability and neurological disability." (PMID 29137225, 2017). "For example, MMP-9 and MMP-7 are upregulated in multiple sclerosis plaques compared to healthy controls." (PMID 37175729, 2023).
multiple sclerosis (continued). "IFN-β decreases serum levels of cytokines such as TNF-α as well as MMP-9 activity and the ratio of MMP-9 and TIMP-1 (an endogenous inhibitor of MMP-9) in blood samples in multiple sclerosis." (PMID 36430870, 2022). "MMPs are effectors of BBB disruption, and extensive studies in multiple sclerosis and experimental autoimmune encephalomyelitis have highlighted the activities of MMP-2 and MMP-9 in BBB disruption." (PMID 26934979, 2016). "IFN-β also reduces the production of MMP-9 by T cells and monocytes in vitro leading to diminished MMP-9 levels in serum of multiple sclerosis patients." (PMID 24023566, 2013). "Minocycline, a potent inhibitor of matrix metalloproteinase (MMP)-9, attenuates disease activity in experimental autoimmune encephalomyelitis (EAE), an animal model of multiple sclerosis (MS)." (PMID 19127301, 2009). "A study of cerebrospinal fluid (CSF) and serum levels of active MMP-9 in patients with the multiple sclerosis found elevated levels of MMP-9 which correlated with disease activity and in particular, the MMP-9/TIMP ratio was found to be pivotal in modulating inflammatory disease activity." (PMID 36016935, 2022). "Furthermore, both anti-inflammatory diets and dietary supplements could decrease production of MMP-9 and, hence, of the 65 kDa MMP-9, as shown in multiple sclerosis." (PMID 35723387, 2021). "It has been shown that the up-regulation of matrix metallopeptidase 9 (MMP-9) increases the permeability of BBB, facilitates the infiltration of leukocytes into the central nervous system, and leads to myelin degradation as well as neuronal damage in multiple sclerosis patients." (PMID 29068387, 2017).
endothelial dysfunction (69 papers, 2010 to 2026). In vascular diseases, endothelial dysfunction is a systemic pathological state of the endothelium (the inner lining of blood vessels) and can be broadly defined as an imbalance between vasodilating and vasoconstricting substances produced by (or acting on) the endothelium. "Among MMPs, MMP-9 (gelatinase B) has received particular attention due to its link with inflammation, endothelial dysfunction, and cardiovascular risk." (PMID 41227041, 2025). "MMP9 has been confirmed to be associated with atherosclerotic thrombosis, endothelial dysfunction, and non-alcoholic fatty liver disease in PCOS patients." (PMID 36942296, 2023). "In early stages, matrix metalloproteinase-9 (MMP-9)-mediated PAR1 activation induces endothelial dysfunction leading to a loss of vascular integrity." (PMID 36319844, 2022). "Our study showed that a higher level of ADMA is associated with a higher level of MMP-9 and IL-1β, indicating inflammation and endothelial dysfunction can promote stenosis dysfunction of VA and lead to shorter duration of VA use." (PMID 33917703, 2021). "The activity of matrix metalloproteinase-9 (MMP-9) is modulated through endothelial dysfunction, inflammatory processes, and matrix breakdown, and it causes the development of atherosclerotic plaque instability." (PMID 32908709, 2020). "In turn, increased activity of MMP-2 and MMP-9 is associated with low-grade inflammation (LGI) and endothelial dysfunction (ED), and increased MMP-9 levels have been associated with renal dysfunction." (PMID 28446168, 2017). "Elevations of ET-1 and MMP-9 in the circulating system have been suggested to be associated with the development of endothelial dysfunction." (PMID 26692905, 2015). "Regarding the molecular biology of this genetic variant, rs3918242 is known to enhance MMP-9 gene expression, which may contribute to endothelial dysfunction, inflammation, and platelet activation—key processes in MPN-related thrombogenesis." (PMID 40724896, 2025). "MMP-2 and MMP-9, in particular, promote thrombus formation by modulating platelet aggregation and endothelial dysfunction." (PMID 40724896, 2025). "MMP-9 links inflammatory signaling to endothelial dysfunction by targeting all three structural tiers that maintain barrier homeostasis, namely: glycocalyx, tight junctions, and basement membrane." (PMID 41304763, 2025). "It is evident in the literature that MMP-9 participates in neutrophil-mediated endothelial dysfunction in systemic lupus erythematosus disease." (PMID 41189711, 2025). "Beyond junctional degradation, MMP-9 destabilizes the neurovascular interface by cleaving basement membrane components and releasing matrix-bound mediators that sustain endothelial dysfunction." (PMID 41304763, 2025). "This includes the inhibition of matrix metalloproteinase-9 (MMP-9)-mediated vascular remodeling, a process linked to endothelial dysfunction and plaque progression." (PMID 41303537, 2025). "In vascular studies where acetylcholine was used, Sugen hypoxia treatment significantly reduced the relaxation response, indicating the involvement of endothelial dysfunction in the development of the disease, which was partially mitigated by MMP9 deletion." (PMID 38001814, 2023). "For a better understanding of the restorative mechanism induced by MMP9 depletion against endothelial dysfunction, we incubated the pulmonary arteries with SOD prior to ACh-induced relaxation." (PMID 38001814, 2023). "MMP-9 mediates the degradation of VE-cadherin and ZO-1 in mechanical stretch-induced endothelial dysfunction." (PMID 34517742, 2021). "In diabetic mice, the increased activity of MMP9 has been shown to play a role in promoting endothelial cell apoptosis and endothelial dysfunction." (PMID 33468174, 2021). "MMP-2 and MMP-9 are colocalized in vessel walls and atherosclerotic plaque, being involved in endothelial dysfunction and DM macrovascular complication and vascular remodeling." (PMID 32093214, 2020).
endothelial dysfunction (continued). "In our data, the expression of IL-6, IL-1β, and MMP-9 increased in the intestinal tissues of the irradiated group and the result suggested that intestinal inflammation is accompanied by endothelial dysfunction in radiation-induced intestinal injury." (PMID 31474856, 2019). "Baicalein displayed anti-inflammatory effects by attenuating endothelial dysfunction and the inflammatory mediators, such as IL-33, IL-6, IL-1β, MMP-9, and IL-13, in radiation enteropathy." (PMID 31474856, 2019). "YKL-40 is a marker of inflammation and endothelial dysfunction, and matrix metalloproteinase 9 (MMP-9) belongs to an enzyme family specialized in breaking down constituents of the extracellular matrix." (PMID 21152016, 2010). "Increased MMP-9 activity in rs3918242 CT genotype carriers may lead to endothelial dysfunction, facilitating a procoagulant vascular surface, increased inflammatory cytokine activity, and enhanced thrombotic potential." (PMID 40724896, 2025). "In addition, curcumin downregulates other inflammatory mediators, including MPO and MMP-9, while modulating nitric oxide metabolites, thereby targeting both inflammatory and oxidative pathways involved in endothelial dysfunction." (PMID 40868165, 2025). "Additionally, PY also decreased the levels of pro-inflammatory cytokines (VEGF and MMP-9) and increased the levels of tight junction-related proteins, suggesting that PY mitigated endothelial dysfunction." (PMID 40584618, 2025). "The impairment of ACh-induced relaxation in SuHx could involve many factors other than MMP9 regulation, even though other reports suggested a more prominent role of MMP9 in endothelial dysfunction." (PMID 38001814, 2023). "Our results emphasized that MMP-9 levels or MMP-9/TIMP-1 ratio could be predictive for endothelial dysfunction." (PMID 34625635, 2021). "The role of MMP-9 in an early stage of endothelial dysfunction is still intriguing." (PMID 32244956, 2020). "MMP-9 is a proteolytic enzyme; these enzymes improve endothelial dysfunction." (PMID 31261815, 2019). "ET-1 and MMP-9 are both endothelial biomarkers that may contribute to the development of endothelial dysfunction and are involved in cardiac remodeling and the development of cardiovascular diseases." (PMID 26692905, 2015). "Decreased NO and oxidative excess may induce matrix metalloproteinases (MMPs), usually MMP-2 and MMP-9, which break down the fibrous cap containing collagen, elastin, and proteoglycans, resulting in endothelial dysfunction." (PMID 25311097, 2014). "At the abluminal surface, MMP-9 degrades basement-membrane scaffolds (collagen IV, laminin), debilitating endothelial anchorage and facilitating leukocyte diapedesis, edema, and capillary leak—core features of endothelial dysfunction, which were summarized across recent reviews." (PMID 41304763, 2025). "The overexpression and activation of MMP-9 by ROS and NF-kB may act as molecular mechanisms to explain the links between chronic intermittent hypoxia, inflammation, and endothelial dysfunction, all of which can lead to cardiovascular disease in patients with OSA." (PMID 40117070, 2025). "This complex inflammatory stimulus triggers early signs of endothelial dysfunction in HAOEC (i.e., upregulation of CXCL8, CXCR2, and MMP9 genes in the presence of variable MMP9 protein activity) but extracellular matrix/angiogenesis-related changes in HAOSMC." (PMID 41227357, 2025). "Beyond impaired elimination, CKD fosters a pro-inflammatory and pro-oxidative vascular milieu that promotes endothelial dysfunction, upregulates CD146 expression, and enhances its shedding via matrix metalloproteinase (MMP-2 and MMP-9) activation." (PMID 40564089, 2025). "RT-qPCR demonstrated that SERPINE1 knockdown significantly downregulated endothelial dysfunction markers, including VCAM1, MMP9, and NOX1." (PMID 41213933, 2025).